CXCL10 (C-X-C motif chemokine ligand 10)
Diseases named in the same sentence as CXCL10 in open-access papers (continued):
Sharing a sentence is not in itself a finding about the gene and the disease.
intestinal tumors (3 papers, 2018 to 2020). "In conclusion, this study demonstrates that Treg reduce endothelial CXCL10 production, inhibit T-cell migration into tumors and that CXCR3 mediated signalling is crucial for lymphocyte accumulation in intestinal tumors." (PMID 29671006, 2018). "A study from the CRC APCmin/+ mouse model suggested that Tregs can inhibit endothelial CXCL10 production, inhibit T cell migration in tumors, and that CXCR3 (receptor of CXCL9, CXCL10, and CXCL11)-mediated signaling is crucial for lymphocyte accumulation in intestinal tumors." (PMID 33419310, 2020). "Our previous study indicated that CXCR3-mediated chemotaxis may be an important means of T-cell recruitment into intestinal tumors as Treg depletion increased the production of CXCL9 and CXCL10 selectively in the tumors." (PMID 29671006, 2018). "This is the first time CXCR3 has been shown to be non-redundant for CD4+ T-cell migration into intestinal tumors, even though earlier results have indicated that CXCL9 and CXCL10 significantly correlate to disease free survival of CRC patients, and also to the recruitment of memory T cells." (PMID 29671006, 2018).
invasive carcinoma of the breast (3 papers, 2021 to 2024). "Lastly, we examined the association of CXCL10 expression with TIL density and immune cell subset infiltration in DCIS and invasive carcinoma of the breast." (PMID 34504204, 2021). "In conclusion, our study showed that CXCL10 promotes tumor cell proliferation, invasion, and immune cell infiltration, implying its contribution in the progression of DCIS to invasive carcinoma of the breast." (PMID 34504204, 2021).
lupus erythematosus (3 papers, 2009 to 2025). An autoimmune, connective tissue chronic inflammatory disorder affecting the skin, joints, kidneys, lungs, heart, and the peripheral blood cells. "CXCL10 has been associated with Th1 type responses in several clinical systems recruiting CXCR3+ effector lymphocytes from the peripheral blood into lupus erythematosus skin lesions, and into inflammatory lesions of the central nervous system." (PMID 19473542, 2009). "Actually, in lupus erythematosus tumidus, a lupus erythematosus subset characterized by dense perivascular lymphocytic infiltration and mucin deposits, CXCL10 were mainly expressed in the perivascular folds, again reflecting the typical inflammatory pattern." (PMID 26385705, 2015). "In lupus erythematosus, IFNs, particularly IFN-κ and IFN-α, amplify inflammatory cascades in the skin characterized by cytokines such as IL-6, IL-1β, and TNF-α, and chemokines (CXCL9, CXCL10), resulting in sustained immune cell infiltration." (PMID 41479908, 2025).
lymphadenitis (3 papers, 2019 to 2024). Acute or chronic inflammation of one or more lymph nodes. "CXCL9/MIG, CCL20, CCL23, CXCL10/IP-10, CXCL1, CXCL2, and CXCL8 significantly declined in our cohort of EPTB (48 TB pleuritis and 57 TB lymphadenitis) patients at both time points." (PMID 36635313, 2023). "CXCL10-expressing inflammatory cells were of grade 1 in 6 (60.0%), and grade 2 in 4 (40.0%) cases of HNL and TB lymphadenitis." (PMID 31101882, 2019).
macular holes (3 papers, 2019 to 2025). A hole in the macula of the retina. "In the macular holes with high myopia, the levels of the inflammatory cytokines C-C motif chemokine ligand 2 (CCL2), C-X-C motif chemokine ligand 10 (CXCL10), and interferon-gamma (IFNG) in the vitreous are significantly elevated." (PMID 40657400, 2025).
mesothelioma (3 papers, 2019 to 2023). A usually malignant and aggressive neoplasm of the mesothelium which is often associated with exposure to asbestos. "The CXCR3 chemokine receptor for CXCL10 is upregulated in murine models of asbestos-induced mesothelioma." (PMID 31867277, 2019). "Our published findings in NSCLC, mesothelioma and ovarian MPE reveal a profound degree of polarization dominated by near nM concentrations of IL-6/sIL6Rα, IL-8, IL10, VEGF, FGF2 and CXCL10." (PMID 37063842, 2023).
metastasis (3 papers, 2020 to 2025). The spread or migration of cancer cells from one part of the body (where they first appeared) to another. "Besides, elevated serum CXCL10 was associated with liver metastasis and poor prognosis in CRC." (PMID 33198757, 2020). "Our study shows that cyclic stretch increases the expression of PD‐L1 and secretion of CXCL10, fostering a “hot” TIME in primary tumors with improved immunotherapy response, as shown in the clinical analysis of primary and liver metastasis NSCLC patients." (PMID 40583158, 2025).
Middle East respiratory syndrome (3 papers, 2022 to 2024). A viral respiratory infection that is caused by the MERS coronavirus (MERS-CoV), which most often manifests with moderate to severe respiratory symptoms, including productive cough and shortness of breath, which can progress to pneumonia and acute respiratory distress syndrome. "Similarly, increased CXCL10 levels are reported in patients with SARS or Middle East respiratory syndrome (MERS)." (PMID 38686377, 2024). "This includes the pro-inflammatory cytokines such as interleukin (IL)-1, IL-6 and tumor necrosis factor (TNF)-α, as well as the inflammatory chemokines CCL-2 and CXCL-10, which have previously been seen in other coronavirus infections such as Middle East respiratory syndrome (MERS)." (PMID 35054471, 2022).
Miscarriage (3 papers, 2024 to 2025). A pregnancy that ends at a stage in which the fetus is incapable of surviving on its own, defined as the spontaneous loss of a fetus before the 22th week of pregnancy. "The CXCR3 ligands CXCL9, CXCL10, and CXCL11 are elevated in spontaneous preterm labor, while CXCL10 is also increased in miscarriages." (PMID 41463301, 2025).
muscle disorders (3 papers, 2023 to 2024). "The mean circulating levels of CXCL10 were 79 ± 53 pg/mL for healthy controls, 180 ± 123 pg/mL for patients with hereditary muscle disorders and 755 ± 783 pg/mL for IIM patients." (PMID 37891738, 2023). "We found CXCL10 levels in hereditary muscle disorders to be no different from in healthy controls; however, another study reported CXCL10 to be significantly elevated in serum and muscle samples of DMD patients, relative to age-matched healthy controls." (PMID 37891738, 2023).
myopia (3 papers, 2022 to 2025). "IL-5 and CXCL10 were significantly higher in high myopia and rhegmatogenous retinal detachment." (PMID 40909333, 2025). "The aqueous humor from mCNV patients contained elevated levels of IL-8 and C−X−C motif chemokine ligand 10 (CXCL10), platelet−derived growth factor (PDGF), IL-2, IL-5, IL-13, IL-15, IL-17A and TNF-α compared to the aqueous humor from simple myopia." (PMID 40909333, 2025).
neurofibroma (3 papers, 2020 to 2024). An intraneural or extraneural neoplasm arising from nerve tissues and neural sheaths. "In the neurofibroma TME, Schwann cells recruit T cells and dendritic cells to the sites of neuroinflammation and neurofibroma lesions via the CXCL10/CXCR3 pathway." (PMID 39429695, 2024).
osteomyelitis (3 papers, 2022 to 2024). An acute or chronic inflammation of the bone and its structures due to infection with pyogenic bacteria. "To test the protective role of CXCL9/10 in an early stage of S. aureus osteomyelitis in mice, we administrated recombinant CXCL9 or CXCL10 to 10-month-old mice with S. aureus osteomyelitis." (PMID 39001897, 2024). "In osteomyelitis, T cells are the primary expressing cells of CXCL10." (PMID 37904457, 2023). "Finally, we identified CXCL10 and MMP1 as the core genes for osteomyelitis and DFU." (PMID 37904457, 2023).
papillary thyroid cancer (3 papers, 2021 to 2025). "The expression level of CXCL10 was corroborated in clinical samples and was found to be considerably elevated in patients with both conditions, more so compared with patients with only papillary carcinoma but less so compared with patients with multiple diseases." (PMID 40063597, 2025).
pneumococcal infection (3 papers, 2014 to 2020). Infections with bacteria of the species streptococcus pneumoniae. "Pneumococcal infection as well increased the mRNA expression levels of pro-inflammatory cytokines and chemokines, including Tnf-α, Il-6, Ccl3, and Cxcl10, which were equally reduced after treatment with Ac2-26." (PMID 33121515, 2020). "The results showed that by 24 h after pneumococcal infection there was a significant increase of protein production of CXCL1, IL-6, TNF-α, CXCL10 and G-CSF in virus/S." (PMID 24408967, 2014).
pneumococcal pneumonia (3 papers, 2018 to 2022). A febrile disease caused by STREPTOCOCCUS PNEUMONIAE. "These experimental data altogether identified serum levels of CXCL9 and CXCL10 as powerful diagnostic biomarkers for pneumococcal pneumonia that should advance toward clinical validation in patient cohorts." (PMID 29988532, 2018).
polymyositis (3 papers, 2014 to 2022). A rare idiopathic inflammatory myopathy characterized by symmetric proximal muscle weakness and elevated muscle enzymes. "We investigated the role of the CXCL10/CXCR3 axis using a murine model of polymyositis based on a previous study on the chemokine profile of human IIM." (PMID 24939012, 2014). "To determine the therapeutic efficacy of CXCL10 blockade, we investigated the role of CXCL10 and the effect of anti-CXCL10 antibody treatment in C protein-induced myositis (CIM), an animal model of polymyositis." (PMID 24939012, 2014). "However, we chose CXCL10 in this study because its expression is abundant in the muscle tissue of CIM in this study and polymyositis unlike CXCL9 or CXCL11." (PMID 24939012, 2014).
Q fever (3 papers, 2017 to 2023). A bacterial infection caused by Coxiella burnetii. "As compared to chronic Q fever patients, acute Q fever patients had higher CXCL10 serum concentrations (median 1204 pg/mL, 180–1439, p < 0.01)." (PMID 28793883, 2017). "In line with this, we report high CXCL10 serum concentrations in human acute Q fever patients during the early stage of their disease." (PMID 28793883, 2017). "Unfortunately, we were unable to test antigen-specific CXCL9, CXCL10, and CXCL11 production in asymptomatic Q fever seropositive controls." (PMID 29804281, 2018). "One limitation is the small group size of QFS patients who recovered from their complaints and missing CXCL9, CXCL10, and CXCL11 data for asymptomatic Q fever seropositive controls." (PMID 29804281, 2018). "In whole blood cultures of chronic Q fever patients, production of all four chemokines was increased upon C. burnetii stimulation, but also healthy controls and past Q fever individuals showed increased production of CXCL9, CXCL10 and CCL8." (PMID 28793883, 2017). "Chronic Q fever patients showed increased production of all four chemokines (CXCL9, CXCL10, CXCL11 and CCL8)." (PMID 28793883, 2017). "Gene expression of the chemokines CXCL9, CXCL10, CXCL11 and CCL8 was strongly up-regulated in C. burnetii stimulated PBMCs of chronic Q fever patients, in contrast to healthy controls." (PMID 28793883, 2017). "Furthermore, a recent study has shown a promising role for chemokines CXCL9, CXCL10, and CXCL11 as potential new biomarkers for persistent infection with C. burnetii, i.e. chronic Q fever." (PMID 29804281, 2018). "Additionally, due to an interassay coefficient of variability well above 15%, we had to exclude data for antigen-specific CXCL9, CXCL10, and CXCL11 production in asymptomatic Q fever seropositive controls." (PMID 29804281, 2018). "Chronic Q fever patients did not have higher levels of CXCL10 or CXCL11 than past Q fever individuals (median 204 pg/mL,10–464 and median 18 pg/mL, 6–72)." (PMID 28793883, 2017). "Further analysis of the CXCR3-chemokine serum concentrations revealed that samples taken within one month after diagnosis of chronic Q fever (n = 9) were significantly higher for CXCL9 (p < 0.05) and CXCL10 (p < 0.05) than samples taken more than 1 month after diagnosis (n = 41)." (PMID 28793883, 2017). "A recent study showed that antigen-specific production of CXCL9 and CXCL11, but not CXCL10, could further help differentiate chronic Q fever patients from Q fever seropositive controls." (PMID 29804281, 2018). "C. burnetii-specific IFNy, IL-2, CXCL9, CXCL10, and CXCL11 production were tested in ex vivo stimulated whole blood of QFS patients who recovered from their complaints (n = 8), QFS patients with persisting complaints (n = 27), and asymptomatic Q fever seropositive controls (n = 10)." (PMID 29804281, 2018). "Although it is tempting to speculate that CXCL10 may be an early marker for acute Q fever, CXCL10 is likely an inflammation marker rather than being specific for acute Q fever." (PMID 28793883, 2017).
Respiratory tract infection (3 papers, 2022). An infection of the upper or lower respiratory tract. "Interferon-inducible chemokines, including CXCL10, could be vital to the host antiviral response in respiratory tract infections by promoting viral elimination prior to the activation of the adaptive immune system." (PMID 36164329, 2022). "CXCL10 and other interferon-inducible chemokines may play a role in the host antiviral response in respiratory tract infections by encouraging viral clearance prior to adaptive immune system activation." (PMID 36164329, 2022).
rhegmatogenous retinal detachment (3 papers, 2020 to 2023). Retinal detachment secondary to retinal tear or break. "Further, CXCL10/IP-10 levels in the vitreous humor of proliferative vitroretinopathy and PDR patients were much higher than that in patients with rhegmatogenous retinal detachment." (PMID 36658547, 2023).
rheumatic diseases (3 papers, 2006 to 2024). "Synovial fluids from patients (n = 126) with rheumatic diseases including RA, AS, PsA and CA were analysed for their CXCL8 and CXCL10 content by specific ELISAs." (PMID 16846531, 2006).
Rickettsiosis (3 papers, 2018 to 2022). A group of infectious diseases that is caused by Rickettsia. "Published findings from the mouse model of rickettsiosis employed in this study yield evidence for increased expression of T cell targeting chemokines CXCL9 and CXCL10 in the lungs and infiltration of CD8+ T cells in the perivascular space around Rickettsia-infected microvessels." (PMID 30687302, 2018). "While no increased expression of CCL-5 was detected in TG rickettsiosis, the expression of CCL-5 and also CXCL-10 was elevated in patients with Mediterranean spotted fever (MSF) caused by R. conorii and RMSF caused by R. rickettsii." (PMID 35543881, 2022).
rosacea (3 papers, 2021 to 2024). A chronic erythematous skin disorder that affects the face. "In patients with rosacea, an increase in circulating serum chemokines CXCL9 and CXCL10 was found, which might provide evidence that rosacea is systematically involved." (PMID 36091020, 2022). "Further verification of the GSE65914 and GSE125733 datasets was performed, and STAT1, which is involved in the regulation of three hub genes (IRF1, IRF8, and CXCL10), was found to be differentially expressed in FFA and rosacea." (PMID 36091020, 2022).
Senile plaques (3 papers, 2012 to 2017). Senile plaques are extracellular deposits of amyloid in the gray matter of the brain. "Astrocytes expressing CXCL10 are commonly associated with senile plaques." (PMID 23078780, 2012).
Splenomegaly (3 papers, 2015 to 2023). Abnormal increased size of the spleen. "A previous study reported on the inflammatory phenotypes in PLD4-deficient mice, such as splenomegaly, and increased concentrations of IFN-γ and CXCL10 in plasma." (PMID 34737744, 2021). "Besides, plasma CXCL10 levels were higher in patients with fever, splenomegaly, lymphadenopathy, and pleuritis." (PMID 38124139, 2023). "We observed a dramatic increase in the expression of several proinflammatory markers such as Il17a, Ifnγ, Tnfα, IL-1β and Ifitm1, and chemokines such as Ccl1, Cxcl10, Ccl22 and Xcl1, in ATMINΔLNBS1ΔL mice displaying splenomegaly, compared to the other genotypes." (PMID 26544571, 2015).
T-cell lymphoma (3 papers, 2013 to 2019). "CXCL10-expressing lymphoid cells were of grade 1 in 9 (90.0%) T cell lymphoma cases, and grade 2 in only 1 (10.0%) case." (PMID 31101882, 2019). "The CXCL10 grade was significantly higher in patients with AOSD than in those with T cell lymphoma, HNL, TB lymphadenitis, and reactive hyperplasia (p < 0.001)." (PMID 31101882, 2019). "Since intraperitoneal injection of bexarotene decreased CXCL5 and CXCL10 mRNA expression in EL4 mouse T-cell lymphoma in vivo, we evaluated serum levels of these chemokines in patients with early and advanced CTCL." (PMID 31616630, 2019). "Furthermore, CXCL10-expressing inflammatory cells of patients with AOSD were higher than those of patients with T cell lymphoma." (PMID 31101882, 2019). "Since intraperitoneal injection of bexarotene decreased expression of CCL22, CXCL5, and CXCL10 mRNA in EL4 mouse T-cell lymphoma, we hypothesized that serum levels of CCL22, CXCL5, or CXCL10 might be associated with response in CTCL patients treated with bexarotene." (PMID 31616630, 2019). "The expression levels of CXCL10 and CXCR3 were higher in patients with AOSD than in those with T cell lymphoma, HNL, tuberculous lymphadenitis, and reactive hyperplasia." (PMID 31101882, 2019). "Furthermore, we found that the CXCL10 and CXCR3 levels were higher in the LNs of patients with AOSD than in those of patients with T cell lymphoma, HNL, TB lymphadenitis and reactive hyperplasia." (PMID 31101882, 2019).
tauopathy (3 papers, 2019 to 2026). Neurodegenerative disorders involving deposition of abnormal tau protein isoforms (tau proteins) in neurons and glial cells in the brain. "Concordantly, CST reduced expression of CD68, GFAP, IL-6, TNF-α, CXCL1, and CXCL10, extending its known peripheral anti-inflammatory actions 20,38 to the central nervous system and establishing CST as a regulator of neuroimmune homeostasis in Tauopathy." (PMID 41509358, 2026). "In addition to regulation of tauopathy, we found that HSF1 overexpression attenuated production of inflammatory molecules such as iNos, Cxcl10, and Il-1β and prevented leukocyte attachment and infiltration, which is a hallmark of vascular inflammation." (PMID 30884523, 2019).
tongue cancer (3 papers, 2012 to 2020). A malignant neoplasm affecting the tongue. "Taken together, our data identify high-level CXCL10 expression as a predictive biomarker for poor response to radiotherapy in tongue cancers." (PMID 24395654, 2014). "In this study, we found that complete response to preoperative radiation is important for survival in tongue cancer patients and that CXCL10 expression could indicate resistance to radiotherapy." (PMID 24395654, 2014). "The sequencing and PCR results in the present study confirmed that the expression levels of CXCL10, CXCL13 and other chemokines in tongue cancer tissues were significantly increased, suggesting their importance in tongue cancer." (PMID 32236620, 2020). "Four novel genes of potential importance in tongue cancer development and maintenance, SH3BGL2, SLC2A6, SLC16A3 and CXCL10, were independently confirmed, validating our data." (PMID 22530001, 2012).
toxoplasmosis (3 papers, 2017 to 2021). A parasitic disease contracted by the ingestion or fetal transmission of toxoplasma gondii. "We then asked if neutrophils could be one of the sources of CXCL8, CCL4, CXCL9, and CXCL10 during toxoplasmosis." (PMID 34607465, 2021). "Moreover, we have also observed that the combined analysis of CXCL9 and CXCL10 improves the accuracy of these biomarkers to diagnose toxoplasmosis." (PMID 33028847, 2020).